RNU5F-4P (RNA, U5F small nuclear 4, pseudogene)
Gene: Small nuclear RNA gene on chromosome 12 (31,594,093 to 31,594,206, reverse strand). Ensembl gene ENSG00000252390.
Homologues: Orthologues: chimpanzee U5 (99% identical), macaque U5 (89% identical). Paralogues in human: RNU5E-4P (75% identical), RNU5E-10P (74% identical), RNU5E-6P (72% identical), RNU5B-4P (71% identical), RNU5E-7P (71% identical), RNU5E-9P (70% identical), RNU5A-4P (69% identical), RNU5A-5P (69% identical), RNU5E-5P (69% identical), RNU5E-8P (69% identical), RNU5F-7P (69% identical), RNU5A-6P (68% identical), and 13 more.